TNF (tumor necrosis factor)
Diseases named in the same sentence as TNF in open-access papers (continued):
Sharing a sentence is not in itself a finding about the gene and the disease.
prostate carcinoma (continued). "In prostate cancer, TNF-α-induced signaling promotes cell survival and therapy resistance." (PMID 40141200, 2025). "Therefore, we then detected the role of CARHSP1 in TNF-α regulation in prostate cancer cells using RT-qPCR assay." (PMID 40055805, 2025). "Pyruvate dehydrogenase kinases such as PDK3 and PDK4 are important markers in glycolysis, have been reported to be used to predict the recurrence in prostate cancer, this might be relevant with the elevated level of lactate and the activation of TNF pathway." (PMID 39811936, 2025). "Furthermore, in patients with prostate cancer, radiotherapy has been shown to induce an inflammatory response, characterised by increased serum concentrations of IL-6, IL-8, TNF-α, and TGF-β." (PMID 40724564, 2025). "Moreover, TNF-α in involved in the initiation of castrate-resistant prostate cancer by inducing hypersensitivity to androgen (in vitro LNCaP cells)." (PMID 39941741, 2025). "We further measured TNF-α expression levels by IHC staining in the prostates of PBCrePten–/–Klf5KR/KR and PBCrePten–/–Klf5+/+ mice and confirmed that Klf5KR knockin significantly induced TNF-α expression in Pten-deficient mouse prostate cancer." (PMID 38781024, 2024). "Depending on the biological context, TNFα can have two distinct roles in prostate cancer." (PMID 39239510, 2024). "Likewise, specific cytokines such as IL-6, TNF-a, IL-15, and IL-1 have been postulated to promote or inhibit cancer cachexia and prostate cancer by affecting several aspects of lipid metabolism." (PMID 38916917, 2024). "Nonetheless, we found divergent results in prostate cancers wherein B7-H3–high tumors displayed negative enrichment of Hallmark IFNγ, IFNα, and TNFα response gene sets." (PMID 38709075, 2024). "The signaling pathways mainly consisted of Th17 cell differentiation, the TNF signaling pathway, PD-L1 expression and PD-1 checkpoint pathway in cancer, leishmaniasis, Hepatitis B, prostate cancer, the AGE-RAGE signaling pathway in diabetic complications, and pertussis." (PMID 39339615, 2024). "Interestingly, another study has reported contradictory results, demonstrating that SULT2B1b knockdown increases TNFα expression in prostate cancer, promoting TNF-mediated apoptosis." (PMID 39280099, 2024). "Moreover, when prostate cancer cells expressing COMP were treated with TNF-α, they exhibited protection against apoptosis." (PMID 38965233, 2024). "TNF is an inflammatory cytokine that play dual roles in cancer, however its role in prostate cancer is still largely unknown." (PMID 38874510, 2024). "In the biology of prostate cancer, TNF-α has contradictory roles." (PMID 39554609, 2024). "In prostate cancer, TNFα plays a crucial role in the constitutive activation of the inflammatory NF-ĸB signaling pathway, which subsequently activates the PI3K/AKT signaling cascade and regulates pro- and anti-apoptotic protein expression to induce anoikis resistance." (PMID 37090717, 2023). "Blackcurrant juice's chemotherapeutic impact on prostate cancer cells is attributed to its mechanistic action, involving cell cycle disruption, decreased TNF‐induced stimulation of cyclooxygenases (COX‐2) activity, and diminished TNF‐induced NF‐κB‐dependent reporter gene transcription." (PMID 37823094, 2023). "Findings were also null for CRP, IL-1β, and TNF-α in these two prostate cancer cohorts." (PMID 37213604, 2023). "KEGG pathway analysis indicated that the modulated target genes are mostly assigned to the NF-κB signaling pathway, TNF signaling pathway, transcriptional misregulation in cancer, prostate cancer, C-type lectin receptor signaling pathway, and IL-17 signaling pathway." (PMID 36532076, 2022).
prostate carcinoma (continued). "Indeed, lycopene exerts significant capacity to inhibit prostate cancer progression demonstrated by reduced levels of inflammatory factors including interleukin (IL)-1, IL-6, Il-8 and tumour necrosis factor-α (TNF-α) in prostate cancer cells in vitro." (PMID 35158943, 2022). "The upstream non-coding RNA hsa_circ_0001165 may regulate TNF expression through hsa-miR-187-3p to induce EMT in prostate cancer cells." (PMID 36513974, 2022). "Since TNF is also the critical death receptor ligand for prostate epithelial cells, we propose that TNF is a multi-purpose, comprehensive signal within the prostate cancer microenvironment that mediated prostate cancer regression following androgen deprivation." (PMID 36551505, 2022). "Since TNF is also the critical death receptor ligand for prostate epithelial cells, we propose that TNF is a multi-purpose, comprehensive signal within the prostate cancer microenvironment that mediates prostate cancer regression following androgen deprivation." (PMID 36551505, 2022). "To determine whether castration induces TNF-dependent vascular damage in a more clinically relevant prostate cancer model, we examined vascular change after castration in the endogenously arising PrCa tumors in PbCre4 × Ptenfl/fl mice." (PMID 36551505, 2022). "We also describe evidence of immunomodulatory intervention of MGF-AuNPs in prostate cancers through observations of enhanced levels of anti-tumor cytokines, such as IL-12 and TNF-α, with concomitant reductions in the levels of pro-tumor cytokines, such as IL-10 and IL-6." (PMID 34408231, 2021). "Additionally, Ingenuity Pathway Analysis suggested a crosstalk between RASAL2 and tumor necrosis factor alpha (TNFα) in prostate cancer." (PMID 34966481, 2021). "Gene Ontology analysis and KEGG pathway enrichment analysis showed that these key targets involve multiple pathways, including prostate cancer, TNF signaling pathway, NF-Kappa B signaling pathway, and JAK-STAT signaling pathway, all of which are closely related to the AMD development process." (PMID 33815556, 2021). "Interestingly, recent findings in prostate cancer cachectic patients showed increased levels of cytokines in circulation: serum TNFα concentration was about 6.54 pg/mL." (PMID 33525436, 2021). "Tumor necrosis factor-alpha (TNFα) induced SK61 phosphorylation, which was associated with enhanced GLI1 expression and GLI1 target genes, including cell cycle regulators CCND1 and n-Myc, in prostate cancer PC3 cells." (PMID 34572373, 2021). "Moreover, they showed that TNFα inhibition with etanercept in castration-resistant prostate cancer cells blocked enzalutamide-induced CCL2 protein secretion and mRNA expression." (PMID 33540543, 2021). "Similarly, we found that SFMBT2 acts as a transcriptional repressor of TNFα gene expression and knockdown of SFMBT2 results in increased expression of TNFα, which activates the NF-κB signaling and plays an important role in prostate cancer progression." (PMID 32971847, 2020). "In summary, the findings of the current meta-analysis indicate that the TNF-α rs1800629, rs361525 and rs1799724 polymorphisms are not correlated with prostate cancer development, although there were some pooled positive results." (PMID 32264962, 2020). "In contrast, miR-130b suppresses angiogenesis in prostate cancer cells by inhibiting TNF-α." (PMID 32993787, 2020). "However, other studies demonstrated that PTEN inhibited the PI3K/AKT/NFκB signaling pathway that is induced by TNFα in human glioma cells, and prostate cancer cells." (PMID 32986377, 2020).
prostate carcinoma (continued). "DU-145 prostate cancer cells respond to TNF-α treatment with an increased expression of PTGS2, of COX-2 and of PGE2 production and this is accompanied by a decreased expression of NAPEPLD without change in NAAA or FAAH expression, thereby producing an imbalance in PTGS2/NAPEPLD." (PMID 33172176, 2020). "Orai1 knockdown or ectopic expression of Orai1 dominant-negative mutants in prostate cancer cells downregulated SOCE activity and decreased susceptibility to diverse apoptosis-inducing stimuli including thapsigargin, tumor necrosis factor-α (TNF-α) and cisplatin." (PMID 31252656, 2019). "A prostate-specific homeobox gene, NKX3.1, could potentiate TNFα/CHX-induced apoptosis in prostate cancer PC-3 cells and LNCaP cells via caspase-3 activation." (PMID 31637258, 2019). "A mathematical model that recapitulates TNF-induced IKK activity could be linked to the model of the NF-κB module and allow us to understand the dynamic control mechanisms in the context of prostate cancer." (PMID 30813597, 2019). "In prostate cancer p38 MAPK activation has been reported via TNFα and IL6." (PMID 30975102, 2019). "Another study demonstrates targeting SULT2B1b may enhance the sensitivity and efficacy to TNF treatment in prostate cancer." (PMID 31655797, 2019). "However, there are papers reporting that TNF-alpha inhibited expression of Fas in the prostate cancer cells." (PMID 30048240, 2018). "We identified 26 miRNAs that may take part in key pathways like TGF-beta, TNF pathways in prostate cancer regulatory networks." (PMID 30027097, 2018). "ANO1 expression is inversely correlated with TNF-α expression in prostate cancer cells." (PMID 29899325, 2018). "To test this hypothesis, we utilized genetic and pharmacological approaches to investigate the effect of ANO1 expression on TNF-α signaling in prostate cancer cells." (PMID 29899325, 2018). "To test this hypothesis, we utilized genetic and pharmacological approaches to investigate the ANO1 expression and TNF-α signaling in prostate cancer cells." (PMID 29899325, 2018). "To understand the mechanism underlying the apoptosis induced by ANO1 inhibition, we performed the gene profiling analysis in prostate cancer PC-3 cells and found that ANO1 downregulation caused an increased expression of death receptor signaling molecules, such as TNF-α, TNFSF10 (TRAIL), and CASP7." (PMID 29899325, 2018). "We identified 26 miRNAs that may take part in key pathways like TGF-beta and TNF pathways in prostate cancer regulatory networks." (PMID 30027097, 2018). "Our novel therapeutic prostate cancer vaccine has been developed by use of GM-CSF/TNFα surface-modified PC-3 cells to treat the patients with advanced prostate cancer, and thus large-scale production of anchorage-dependent PC-3 prostate cancer cells will be required for vaccine manufacturing." (PMID 28945791, 2017). "In this study, we developed a rapid strategy to screen a serum-free medium for culturing the anchorage-dependent PC-3 prostate cancer cells, which was going to be prepared in large scale to generate GM-CSF/TNFα-surface-modified whole cell prostate cancer vaccine." (PMID 28945791, 2017). "B cells may also directly promote carcinogenesis through local elaboration of inflammatory mediators such as TNF-α in squamous cell skin cancer, lymphotoxin in prostate cancer, and IL-8 in bladder cancer." (PMID 27437104, 2016). "Thus, our findings of the increased levels of IL‐7, IL‐8, and TNF‐α in patients with prostate cancer are consistent with characteristic features of prostate cancer reported previously." (PMID 26880719, 2016). "TNF-α has been shown to induce apoptosis in human prostate cancer cell lines mainly through the NFκB pathway, however, it appears that this may be partly dependent upon androgen sensitivity." (PMID 26912236, 2016).
prostate carcinoma (continued). "As PC3 prostate cancer cells are known to express TNF-α at the mRNA level, we also aimed to assess whether over-expression of ADAM19 in these cells may promote shedding of endogenous TNF-α." (PMID 26912236, 2016). "Indeed, expression of multiple cytokine receptors including IL-6 and TNF-α is increased in prostate cancer in comparison to control tissue, and rises with Gleason grade." (PMID 26376613, 2015). "Our previous studies have shown that apigenin suppresses NF-κB activation in prostate cancer cells and sensitize them to TNFα-mediated apoptosis and we further validated our hypothesis in in vivo model." (PMID 26379052, 2015). "Tumor necrosis factor-alpha (TNF-α) is an important inflammatory cytokine that may play a role in controlling the progression of prostate cancer." (PMID 24666463, 2014). "Furthermore, Id1 protein expression in prostate cancer cells mediated resistance to apoptosis induced by TNFα." (PMID 24378760, 2014). "Also, TNF-α levels have been suggested as a potential biomarker for prostate cancer as these are generally higher in tumor tissue than in normal tissue." (PMID 25419573, 2014). "TNF-α is a pro-inflammatory molecule that may play an important role in the development of the immune response and affect the progression of prostate cancer." (PMID 24666463, 2014). "Herein, we used human cervix and prostate carcinoma cells as a model system for DR-triggered apoptosis to interrogate whether miR-133b is capable of modifying the cellular death response to TNFα, Fas/CD95 ligand (FasL) or TRAIL." (PMID 22532850, 2012). "Also pathway analysis results indicated the TNF-α/NF-κB signaling pathway as being significantly dysregulated in prostate carcinoma formation." (PMID 23185449, 2012). "A presentation at the 26th annual meeting of the European Association of Urology in 2011 revealed that serum levels of proinflammatory cytokines, including TNF-α, increased 2 days after administration of docetaxel to patients with castration-resistant prostate cancer." (PMID 22225778, 2012). "An increase in the levels of cleaved caspase 8 in the PC3 tumor lysates from simvastation-treated mice indicate that one or both of the Fas-L and TNF-mediated death-receptor signaling pathway is involved in simvastatin-induced apoptosis in prostate cancer cells." (PMID 22974127, 2012). "Therefore, we evaluated the pro-apoptotic effect of cadmium in combination with TNF-α on prostate cancer cells." (PMID 20618956, 2010). "We identified that fetal bovine serum, some growth factors (epidermal growth factor, androgen, insulin-like growth factor-I, and hepatocyte growth factor) and cytokines (TNFα and interleukin-1beta) induced midkine expression in a human prostate cancer cell line LNCaP cells." (PMID 18275606, 2008). "Furthermore, midkine expression was significantly increased in late stage prostate cancer, which coincides with previously reported high serum levels of TNFα in advanced prostate cancer." (PMID 18275606, 2008). "It is of interest that many androgen-insensitive prostate cancer cells are TNF-α insensitive." (PMID 15150588, 2004). "In this study, we have measured serial levels of serum IL-6 and TNF-α in prostate cancer patients." (PMID 15150588, 2004). "In conclusion, these results suggest that IL-6 and TNF-α correlate with the extent of disease in patients with prostate cancer and may be monitored in conjunction with other disease markers." (PMID 15150588, 2004). "Both IL-6 and TNF-α were detectable in all control subjects and prostate cancer patients." (PMID 15150588, 2004). "However, the result indicated that the effect of CARHSP1 knockdown on TNF-α mRNA was not consistent among different prostate cancer cell lines, which suggests that there are other factors in prostate cancer cells interfering with the regulation of CARHSP1 on TNF-α." (PMID 40055805, 2025).
prostate carcinoma (continued). "Mechanistically, we found that SERPINA3 may influence the expression of CXCL2 to activate the IL-17 and TNFα signaling pathways, thereby mediating the recruitment of M1 macrophages in the tumor microenvironment and exerting an inhibitory effect on prostate cancer progression." (PMID 40367014, 2025). "The in vivo anti-tumor effects of 5a-HSA, alone and in combination with S-NGR-TNF (a vessel-targeted derivative of tumor necrosis factor-a), were investigated in various murine tumor models, including pancreatic ductal adenocarcinoma, fibrosarcoma, prostate cancer, and mammary adenocarcinoma." (PMID 40055773, 2025). "Moreover, TNFα sensitises prostate cancer cells to ionizing radiation." (PMID 39239510, 2024). "In addition, our result showed that formononetin could target and induce the expression of TNF in prostate cancer cell." (PMID 38874510, 2024). "Furthermore, we observed reduced amounts of IFN-γ and TNF in the supernatants of palbociclib-treated PSCA-specific UniCAR T cells and CD3-PSCA bsAb-engaged T cells co-cultured with prostate cancer cells, which is caused by the palbociclib-mediated decrease in T cell numbers." (PMID 36817127, 2023). "In prostate cancer, a high lipid diet may accelerate tumor cell proliferation by increasing levels of insulin-like growth factor 1, IL-1α, IL-1β, IL -6, or TNF-α or through activation of signaling pathways such as MCP-1/CCR2 (monocyte chemoattractant protein-1/C-C Motif Chemokine Receptor 2)." (PMID 38028534, 2023). "Pathway-enrichment analyses showed that the active components of ARC could treat GA by regulating signaling pathways such as prostate cancer (hsa05215), C-type lectin receptor signaling pathway (hsa04625), TNF signaling pathway (hsa04668) and endocrine resistance (hsa01522)." (PMID 33995019, 2021). "Therefore, suppressing ANO1 or enhancing TNF-α signaling may serve as a therapeutic strategy for potential treatment of human prostate cancer." (PMID 29899325, 2018). "Nothing is known as to whether TNFα affects the eCB system in prostate cancer cells." (PMID 28910408, 2017). "After the titles and abstracts were reviewed, 66 of these articles were excluded: 46 were not related to gene polymorphisms, 17 articles discussed polymorphisms other than –308G/A and/or –238G/A of TNF-α, 1 was not closely relevant to prostate cancer, and 2 were meta-analyses." (PMID 24666463, 2014). "Our results suggest that while the TNF-α-238G/A polymorphism may not be associated with prostate cancer the TNF-α-308C/T polymorphism may significantly contribute to prostate cancer susceptibility in healthy volunteers." (PMID 24666463, 2014). "Therefore, it is possible that increased MDK expression the in late stage prostate cancers may be induced by increased systemic and/or local TNFα and other factors as identified in this study." (PMID 18275606, 2008). "Pro-inflammatory cytokines, such as tumor necrosis factor-alpha (TNF-α) and interleukin-17 (IL-17), are key components of the inflammatory milieu in prostate cancer." (PMID 40141200, 2025). "First, network pharmacology was used to predict the potential targets of Osthole, identifying 68 targets shared with prostate cancer, including AKT1, TNF, IL6, STAT3, and CTNNB1." (PMID 40978029, 2025). "In their pilot study with 15 prostate cancer patients, they evaluated the effects of a 24-week HOET on IL-1α, IL-5, IL-6, IL-12, TNF-α, and IFN-γ." (PMID 40498221, 2025). "Mechanistically, it confers cytoprotection in prostate cancer by regulating PKC isoform translocation and inhibiting PKC-dependent TNF-α release." (PMID 41208974, 2025).